INS (insulin)
Diseases named in the same sentence as INS in open-access papers (continued):
Sharing a sentence is not in itself a finding about the gene and the disease.
Insulin resistance (continued). "Further, it is important to investigate potential metabolic processes by which such neurocognitive impairments may arise, such as via elevated circulating insulin levels and concomitance insulin resistance, to inform methods by which such deficits can be addressed through intervention or prevention." (PMID 28093279, 2017). "Early initiation of basal insulin has been used not only in type 1 diabetes but also in type 2 diabetes; nevertheless, some patients will develop insulin resistance, and higher doses of insulin may be required to lower the blood glucose which can lead to weight gain and the risk of hypoglycemia." (PMID 28538386, 2017). "Free fructose caused insulin resistance, but did not affect insulin sensitivity in this study." (PMID 29191195, 2017). "Moreover, our results indicate that post-receptor defects in insulin signalling may contribute to insulin resistance in DM patients despite the aberrant alternative splicing of INSR gene." (PMID 28915272, 2017). "While emerging evidence suggest that dysregulation of neuronal insulin signaling, so-called cerebral insulin resistance, may play central role in cognitive dysfunction, the exact mechanisms by which T2DM influences the cognitive function and dementia risk are yet to be elucidated." (PMID 29249964, 2017). "Thus, the main causes of insulin resistance are thought to include significant decreases in IRS-1 protein levels, insulin-stimulated IRS-1 tyrosine phosphorylation, and IRS-1-associated PI3K activity observed in subjects with insulin resistance and type 2 diabetes." (PMID 29259227, 2017). "They directly cause insulin secretory defects in animal and cell culture models and may promote insulin resistance in nondiabetic subjects." (PMID 28695132, 2017). "Furthermore, the negative associations between circulating ghrelin and insulin resistance, as well as insulin levels in this study are consistent with those found in a large population-based study." (PMID 28146431, 2017). "The reduced SIRT-1 functionality could be the consequence of OS and is likely linked to hepatic fibrosis, microsteatosis and impaired hepatic insulin signaling and glucose transporters, leading to insulin resistance and glucose intolerance observed at adulthood." (PMID 29018245, 2017). "However, study that provided whether insulin/insulin resistance is playing a role in linking BMI or WC with BP is limited." (PMID 28710353, 2017). "Thus, some factors might be mostly released during the period of preserved insulin sensitivity, and then their release will be altered as insulin resistance develops." (PMID 28286777, 2017). "However, it remains unknown whether altering glucose tolerance and insulin resistance regulates insulin-mediated Akt signaling-related GRK2 in T2DM models." (PMID 28814745, 2017). "The increase in glucose AUC during the OGTT, and the markedly higher percentage of IPH in the 90-min compared with the 60-min group, could be explained by a reduction in total insulin secretion, as insulin resistance measures (based on HOMA-IR and the Matsuda index) were similar in both groups." (PMID 29216249, 2017). "One explanation for differences in IGT may be increased levels of skeletal muscle use, i.e., higher exercise levels, since physical activity has been linked to insulin sensitivity and lack of exercise leads to skeletal muscle insulin resistance and IGT." (PMID 29165385, 2017). "We have analysed the insulin pathway in skeletal muscle biopsies and in myotube cultures from DM patients to assess whether downstream metabolism might be dysregulated and to better characterize the mechanism inducing insulin resistance." (PMID 28915272, 2017). "However, women with underlying pre-existing metabolic disturbances (pre-gestational insulin resistance and chronic β cell dysfunction with relative insulin secretion defect) are unable to upregulate the insulin secretion and develop the clinical picture of gestational diabetes." (PMID 28644881, 2017).
Insulin resistance (continued). "The measurement of insulin at 3 d after IMI might have missed the temporary insulin resistance." (PMID 28740504, 2017). "Physiological levels of adiponectin regulate insulin sensitivity by increasing FA-metabolism and energy expenditure in muscle and have anti-inflammatory effects, while decreased adiponectin levels have been shown to correlate with development of insulin resistance." (PMID 28445413, 2017). "Thus, high insulin levels may be beneficial to the brain early on in the context of hyperinsulinemia and peripheral insulin resistance." (PMID 29403343, 2017). "Insulin resistance likely also plays a role in promoting the PCOS reproductive phenotype as insulin has been shown to increase theca androgen production and may mediate some of the ovarian morphology characteristics commonly seen in PCOS by driving theca cell proliferation." (PMID 28620546, 2017). "Notably, there is a theoretical concern that chronic high insulin levels with prolonged intranasal insulin treatment may induce cerebral insulin resistance." (PMID 28282917, 2017). "We speculate that prolonged treatment with high doses of exogenous insulin in these patients could contribute to the accumulation of dysfunctional mitochondria and abnormal morphology and thereby generating a vicious cycle maintaining insulin resistance." (PMID 28252104, 2017). "Another recently published study suggested that biochemical hypoglycemia might be associated with insulin secretion rather than insulin resistance." (PMID 28913363, 2017). "Thus, it might suggest that exenatide is another insulin sensitizer that leads to amelioration of insulin resistance in obese patients with T2D." (PMID 29358950, 2017). "Particular adaptation in insulin sensitivity during pregnancy could explain why most of the previous reported cases showed suggestive hypoglycemic signs by week 16 of gestation, before insulin resistance appeared." (PMID 28427440, 2017). "In both groups, copeptin levels were higher in participants with metabolic syndrome with positive correlation with insulin levels and HOMA-IR and independent association with adiposity and dyslipidemia, suggesting that copeptin may be a novel marker of insulin resistance and metabolic syndrome." (PMID 27473078, 2017). "Regarding insulin resistance mechanisms, Sun and colleagues reported that gene expression of miR-181b was decreased in adipose tissue and endothelial cells of obese mice, impairing glucose homeostasis, insulin sensitivity and promoting adipose tissue inflammation." (PMID 29044172, 2017). "Therefore, brain insulin resistance and subsequent hyperphosphorylation of tau, which are found in this model, are appropriate for the investigation of the beneficial role of intranasal insulin on tau hyperphosphorylation." (PMID 28382978, 2017). "Insulin resistance could also decrease the AMPK phosphorylation and increase the expression levels of SREBP-1c, which further suppressed IRS-1 activation, inhibits IRS-1-associated insulin signaling and thereby decreases glucose uptake and utilization." (PMID 28867797, 2017). "However, increase of the insulin growth factor-1 (IGF-1) level, especially within the first months of treatment, may temporary improve insulin sensitivity, even in patients with pre-existing insulin resistance." (PMID 28397183, 2017). "Together with an acetate-induced partial inhibition of intracellular lipolysis in adipocytes this might result in reduced fat accumulation and improved insulin action in peripheral tissues such as skeletal muscle, liver and pancreas, thereby preventing insulin resistance." (PMID 28539646, 2017). "Thus, in our present study, AT redistribution to a more insulin-sensitive tissue could also have participated in the beneficial effects of epididymal lipectomy on IH-induced insulin resistance." (PMID 28894286, 2017).
Insulin resistance (continued). "Furthermore, rs13175330 G allele carriers in the HTN w/o therapy group had significantly increased levels of insulin, insulin resistance, and oxidized low-density lipoprotein (LDL) and significantly decreased LDL-cholesterol levels and LDL particle sizes compared to the AA carriers." (PMID 29162152, 2017). "Although the FATZO mouse becomes obese, has significant insulin resistance, hyperlipidemia and hyperglycemia, under the conditions of these experiments it does not develop severe hyperglycemia with low concentrations of insulin that would indicate beta cell loss." (PMID 28640857, 2017). "This might be a reason why only high glucose levels, and not insulin and insulin resistance, show risk association." (PMID 29233100, 2017). "Importantly, a stimulation comparable to maximal insulin and metformin was observed at 5 μM RA, indicating a potential for RA to be used similar to metformin as a pharmacological intervention in the treatment of insulin resistance." (PMID 28991159, 2017). "Although chronic elevation of IL-6 is typically regarded as detrimental to insulin resistance and cardiovascular health, acute oscillations in IL-6, as seen for example following exercise, may be important in maintaining insulin sensitivity in muscle post-exercise." (PMID 26514561, 2017). "In combination, these findings support the hypothesis that South Asians exhibit long-term beta cell compensation for chronic insulin resistance from childhood and that they are unable to produce further beta cell compensation in response to decreasing insulin sensitivity above 60 years of age." (PMID 28409212, 2017). "Another study has shown that ginsenoside Rb1 activates the insulin signaling pathway, upregulates the expression and translocation of glucose transporters in adipose tissue, and thus increases glucose uptake in adipocytes, thereby reducing blood glucose levels and improving insulin resistance." (PMID 29164155, 2017). "Insulin is a key regulator of lipid and glucose metabolism; elevated plasma insulin levels may incur obesity and insulin resistance, and impaired insulin sensitivity often accompanies increased glucose production and lipolysis and reduced glucose uptake in the liver." (PMID 27792149, 2016). "Current findings suggest that metabolic acidosis is linked to insulin resistance in diabetic, Chronic Kidney Disease (CKD) patients and oral bicarbonate administration may correct metabolic acidosis that, in turn, improves insulin sensitivity in this population." (PMID 27770799, 2016). "Thus, the aim of this review is to provide current evidence on the potential benefits of inositol isomers (MYO-INS and DCI) in the treatment of disease associated to insulin resistance such as polycystic ovary syndrome (PCOS), gestational diabetes, and metabolic syndrome." (PMID 27688754, 2016). "Conversely, selective insulin resistance in the PT could result in the preservation of the stimulatory effect of insulin on sodium transport as well as the attenuation of inhibitory effect of insulin on gluconeogenesis." (PMID 27247938, 2016). "Therefore, central insulin resistance which is a characteristic of the metabolic syndrome, may reverse the normal effects of brain insulin to support optimal baroreflex control." (PMID 27857694, 2016). "In line with views, we observed that HOMA-IR increased with plasma selenium quartiles in this study (P < 0.001), which indicate that high circulating selenium levels is correlated with impaired insulin signaling and could potentially modulate liver insulin resistance." (PMID 27853246, 2016). "Also, WT mice on Western diet had a blunted response to insulin, indicative of insulin resistance." (PMID 26890135, 2016). "However, the extent to which local and systemic elevation of cytokines, such as monocyte chemoattractant protein 1 (MCP-1), interferes with the action of insulin and promotes insulin resistance and glucose intolerance in muscle remains unclear." (PMID 26661101, 2016).
Insulin resistance (continued). "For example, high basal insulin levels could promote insulin resistance." (PMID 27098609, 2016). "The association between HCV positivity and insulin resistance is well recognized and may involve an HCV-related impairment of insulin signaling, production of proinflammatory cytokines and induction of liver fibrosis resulting in a reduced hepatic and systemic insulin sensitivity and responsiveness." (PMID 26735686, 2016). "Reasoning that increased expression of the candidate gene in insulin-resistant tissue could indicate that the gene contributes to insulin resistance, we examined whether mRNA expression of any candidate gene was upregulated in high-fat diet (HFD) fed, insulin resistant mice." (PMID 27577745, 2016). "To investigate the cell-autonomous mechanisms that may mediate the effects of maternal nutrition on susceptibility to developing peripheral insulin resistance in WAT in the offspring, we studied miRNAs implicated in regulating the synthesis of programmed insulin signalling proteins." (PMID 26965244, 2016). "While this transient insulin resistance may seem contradictory to the beneficial effects of exercise on insulin action, prior studies have reported that exercise increases hepatic glucose production and raises lipolysis in the immediate post-exercise interval in an intensity dependent manner." (PMID 27111219, 2016). "For instance, dietary supplementation with BCAA, which improves insulin resistance and glucose tolerance in chronic liver disease patients, significantly suppresses liver tumorigenesis in obese and diabetic mice by decreasing serum insulin levels as well as improving insulin sensitivity." (PMID 26871288, 2016). "Taken together, these studies indicate that insulin resistance might promote downregulation of VEGF, causing vascular rarefaction which may accelerate further development of insulin resistance due to insufficient delivery of insulin." (PMID 26892461, 2016). "Our findings suggest that normolipidemic severe insulin resistance without fatty liver and with preserved or elevated adiponectin may be indicative of proximal insulin signaling defects generally, rather than loss of receptor function specifically." (PMID 27766312, 2016). "Interestingly, treatment of these subjects with the insulin sensitizing drug rosiglitazone enhanced insulin sensitivity and reduced plasma concentration of ADMA, a correlation that remained significant even after adjusting for risk factors associated with insulin resistance." (PMID 26770984, 2016). "While age‐related insulin resistance and hyperinsulinemia are usually considered to be secondary to changes in muscle, the liver also plays a key role in whole‐body insulin handling and its role in age‐related changes in insulin homeostasis is largely unknown." (PMID 27095270, 2016). "In addition, hypoxia is known to encourage insulin synthesis and release by pancreatic β-cells, creating an acute or chronic physiological state resulting in blood insulin accumulation and perhaps perceived insulin resistance." (PMID 27274997, 2016). "However, insulin resistance will not lead to the onset of type 2 diabetes unless it is accompanied by pancreatic β cell failure, as β-cells can respond by upregulating insulin secretion to maintain normoglycemia when insulin resistance occurs, a process known as β-cell compensation." (PMID 27861641, 2016). "Finally, insulin, in the context of insulin resistance, prompts fibrogenesis by stellate cells." (PMID 27973438, 2016). "However, associations between quality aspects of diet, markers of glucose and insulin metabolism, and risk of glucose tolerance abnormalities such as impaired fasting glucose (IFG) and impaired glucose tolerance (IGT), and insulin resistance (IR) remain to be investigated." (PMID 27869717, 2016).
Insulin resistance (continued). "However, given that low HDL cholesterol and high TAG are frequently found with insulin resistance, it is possible that decreased insulin sensitivity could be a possible mechanism for higher postprandial glucose concentrations in the S447 homozygotes." (PMID 26999119, 2016). "This combination may in turn exacerbate fat-induced insulin resistance and decreased insulin sensitivity in the brain, and impaired clearance of Aβ peptide across the brain-blood barrier, to which the very old brain with excess vascular pathology may be particularly susceptible." (PMID 26740685, 2016). "Reducing the quantity of carbohydrates in the diet may be an important strategy for reducing the risk of T2DM in youth via demonstrated effects on fasting insulin, insulin resistance, and glycaemic status, irrespective of weight change." (PMID 27517953, 2016). "Insulin resistance (IR) is typified by a decrease in the sensitivity of insulin responsive cells such as myocytes, adipocytes, hepatocytes, and pancreatic β-cells to normal circulating levels of insulin which can in turn be manifested as impair glucose tolerance and subsequently type 2 diabetes." (PMID 27826244, 2016). "Indeed, insulin signaling has been found to be impaired in brains of patients with AD; and type 2 diabetes, characterized by insulin resistance or lack of insulin, has been proposed as a risk factor for AD." (PMID 27656889, 2016). "Desensitization of tissues to insulin and insulin resistance led to a compensating increase in pancreatic insulin production called hyperinsulinemia, which may have possible direct oncogenic effects on proliferative and anti-apoptosis signaling in cancer cells." (PMID 27610222, 2016). "Insulin sensitivity is the ability of insulin to decrease plasma glucose levels by suppressing hepatic glucose formation and stimulating glucose utilization in skeletal muscle and adipose tissue, while insulin resistance is described as an impaired biological response to insulin." (PMID 27087404, 2016). "On the basis of the potential role of RAGE in adipogenesis, inflammation, and insulin resistance, we explored whether its expression in EAT was associated with EAT adiposity and the metabolic dysfunctions, such as impaired insulin signaling, normally found in CAD patients." (PMID 26788516, 2016). "In addition, IL-33-treated mice showed a significant decrease in the severity of HFD-induced insulin resistance and glucose intolerance, which were indicated by changes in plasma levels of glucose in response to a peritoneal injection of insulin and glucose, respectively." (PMID 27172901, 2016). "Some metabolically active lipids inhibit insulin signalling and may promote insulin resistance." (PMID 27212806, 2016). "PI3K/Akt activation by insulin might contribute to the development of insulin resistance." (PMID 27257845, 2016). "Since IL-37 ameliorates insulin resistance and obesity-induced inflammation, it will be important to address whether IL-1R8 is involved in these contexts, preserving glucose tolerance and insulin sensitivity and reducing inflammation in the adipose tissue." (PMID 27148268, 2016). "Thus, disrupted or hampered calcium metabolism in calcium signaling could result in ER stress and insulin resistance or decreased insulin secretion." (PMID 27736926, 2016). "Thus, it is possible that insulin estrogenization may contribute to insulin resistance by disrupting insulin structures or by blocking insulin signaling." (PMID 27353345, 2016). "In addition, it has been shown that IL-18 mRNA and plasma IL-18 correlated with insulin resistance, suggesting that training-induced reduction in IL-18 expression may be a contributing mechanism to improve insulin sensitivity after training." (PMID 26788518, 2016).